YWHAH-AS1 (YWHAH antisense RNA 1)
Synonyms: C22orf24; HSN44A4A
Gene: Long non-coding RNA gene on chromosome 22 (31,907,140 to 31,945,518, reverse strand). Ensembl gene ENSG00000128254.
Subcellular location: Membrane